RPL10P9 (ribosomal protein L10 pseudogene 9)
Synonyms: RPL10_1_637
Gene: Processed pseudogene on chromosome 5 (168,616,352 to 168,616,996, forward strand). Ensembl gene ENSG00000233913.
Diseases named in the same sentence as RPL10P9 in open-access papers:
RPL10P9 is named in the same sentence as 2 diseases in open-access papers, as found by Europe PMC text mining. Sharing a sentence is not in itself a finding about the gene and the disease. The quoted sentences say what the papers report.
substance abuse (1 paper, 2020). The use of a drug for a reason other than which it was intended or in a manner or in quantities other than directed. "Of these genes, in neurons, ribosomal RPL10P9 pseudogene showed over tenfold upregulation in violent offenders as compared with healthy controls and nonviolent individuals with substance abuse." (PMID 31455857, 2020).
neoplasia (1 paper, 2025). "After adjusting for clinical covariates, we identified only two genes with altered expression with progressive stages of neoplasia: increased LAIR2 and decreased RPL10P9." (PMID 40844321, 2025).